SOX9 (SRY-box transcription factor 9)
Diseases named in the same sentence as SOX9 in open-access papers (continued):
Sharing a sentence is not in itself a finding about the gene and the disease.
adenoma (18 papers, 2010 to 2025). A neoplasm arising from the epithelium. "The authors reported Sox9 inactivation prevented Apc-mutation–induced adenoma formation, reduced an aberrant stem cell–like signature, and prolonged survival compared with Apc inactivation on its own." (PMID 40179020, 2025). "Consistent with findings in mice, multilineage differentiation capacities were restored upon Sox9 knockdown in adenoma organoids derived from APC-mutant human colonic tissues." (PMID 37894295, 2023). "Specifically, the ablation of Sox9 in adenomatous polyposis coli (Apc)-deleted mice reduced the AbSC frequency, and, therefore, in vivo adenoma formation." (PMID 37894295, 2023). "Immunofluorescence analysis confirmed a corresponding decrease in the Lgr5-GFP+ tumor cell area and Sox9+, Prox1+, and Cd24+ adenoma cells in the intestinal sections 18 days after Lef1 deletion." (PMID 34788095, 2021). "Moreover, to determine the strength of association between SOX9 tumor expression level and GH- secreting pituitary adenoma, the odds ratio was calculated that it was revealed that SOX9 tumor expression level significantly affect adenoma incidence by the odds ratio of 8.4 (P = 0.015)." (PMID 33736633, 2021). "On the other hand, the Wnt target gene Sox9 expression was significantly upregulated in all mutant adenomas when compared to control (Fig EV3G–J and O), suggesting that Wnt signalling is upregulated upon Nedd4 and Nedd4l loss." (PMID 31867777, 2020). "In vivo, Sox9 was markedly induced in Apc-mutant adenomas, but showed limited and mosaic expression in P-Rspo3 lesions, mirroring normal intestinal crypts." (PMID 28695896, 2017). "IRS for SOX9 in adenomas compared to normal mucosa was 1.9 (± 0.1) vs. 0.7 (± 0.1) in the control group (H2O) (P ≤ 0.01) compared to 2.0 (± 0.1) vs. 0.8 (± 0.1) in the TRD group (P ≤ 0.001)." (PMID 20442801, 2010). "The cell cycle regulator Cyclin-D1 and the transcription factor SOX9 displayed a significantly increased expression in adenomas compared to normal mucosa." (PMID 20442801, 2010). "In our study, adenomas were characterized by significantly higher SOX9 expression compared to normal mucosa suggesting an important role in this paradigm of UC-associated CRC." (PMID 20442801, 2010). "Supporting a role for Jag1 in adenoma formation and by extension in tumor-initiating cell (TIC) activity, Jag1 KO adenomas expressed reduced levels of Lgr5, Bmi1, Ephb2, c-Myc, Sox9, and Cd133 compared to the Jag1 WT, as determined by qRT-PCR and in situ hybridization (ISH)." (PMID 30065304, 2018). "Notably, the authors did not detect any adenomas with the expected Cre-mediated biallelic inactivation of Sox9, which led the authors to conclude Sox9 inactivation blocks Apc mutation–induced adenoma initiation." (PMID 40179020, 2025). "In C2 goblet cells, during the process from normal colon to adenoma and from adenoma to carcinoma, several continuously highly expressed genes were found, including DEFA6, SOX9, ID1, L1TD1, CXCL3, and ODC1." (PMID 36944972, 2023). "And the 6 coincident genes significantly enriched in adenoma and carcinoma were DEFA6, SOX9, ID1, L1TD1, CXCL3, and ODC1." (PMID 36944972, 2023). "In the experimental intestinal tumor model of APCMin/+ mice, expression of Sox-9 and PRDM1 were significantly elevated in murine adenoma by gastrointestinal ribosomal dysfunction." (PMID 33972671, 2021). "While Sox9 is normally confined at the bottom of the intestinal crypt compartment where intestinal stem cells reside, this HMG-box transcription factor is strongly expressed in poorly differentiated lesions and early-stage adenomas." (PMID 37894295, 2023). "In contrast, typical adenoma cells produced in elderly APCMin-Villin-GFP mice displayed the opposite expression pattern, being positive for AB-PAS staining, exhibiting high levels of Sox9 expression, and reduced CDX2 expression." (PMID 37923722, 2023).
adenoma (continued). "Expression changes detected by RNA-seq were validated in an expanded set of samples by RT-qPCR for IL10, SOX9, GBX2, and HOXA5, genes with biological functions that may contribute to the reduced progression of hyperplasia to adenoma." (PMID 33632299, 2021). "Immunhistochemistry revealed increased expression of Ki-67, β-catenin, SOX9 and Cyclin-D1 in adenomas compared to normal mucosa – without significant difference between TRD and control treatment." (PMID 20442801, 2010). "SOX9 and ARID5B were mutated in the adenoma group but not in the cancer group." (PMID 37546388, 2023). "To investigate if high Sox9 expression is conserved in a GEMM of lung ADC, we stained lung adenoma and ADC sections from the LSL-K-rasG12D lung ADC mouse model for Sox9 and observed Sox9 protein expression to be mostly absent from normal lung and adenoma tissue, but highly expressed in ADC tumors." (PMID 25004243, 2014). "One study reported Sox9 inactivation in mouse intestinal epithelium increased the number of large adenomas and overall tumors in Apcmin/+ mice, but there was no description of whether Sox9 inactivation affected biological characteristics of the adenomas arising." (PMID 40179020, 2025).
non-small cell lung carcinoma (18 papers, 2012 to 2025). A group of at least three distinct histological types of lung cancer, including non-small cell squamous cell carcinoma, adenocarcinoma, and large cell carcinoma. "SNHG1 promotes non-small cell lung cancer tumorigenesis and progression via the miR-101-3p/SOX9/Wnt/β-Catenin axis." (PMID 39519092, 2024). "In another study, TGF-β secreted by TAMs was shown to promote metastasis in non-small cell lung cancer (NSCLC) through promoting TGF-β/SOX9 axis expression." (PMID 35201514, 2021). "Additionally, the overexpression of SOX9 in non-small cell lung cancer was correlated with tumor size and tumor severity." (PMID 33736633, 2021). "In non-small cell lung carcinoma (NSCLC), SOX9 contributes to tumor development and growth." (PMID 38275880, 2024).
Cirrhosis (16 papers, 2012 to 2025). A chronic disorder of the liver in which liver tissue becomes scarred and is partially replaced by regenerative nodules and fibrotic tissue resulting in loss of liver function. "Another research group, analyzing databases (GSE89377 and GSE139602), found that elevated SOX9 expression is associated with heightened immune infiltration, suggesting its potential as a biomarker for cirrhosis diagnosis or therapeutic targeting." (PMID 39974732, 2025). "The Cirrhosis Risk Score (CRS) gene includes SOX9, which acts as an indicator for liver progenitor cells." (PMID 39974732, 2025). "SOX9 positivity was significantly associated with male gender (p< 0.021) and presence of cirrhosis (p<0.022)." (PMID 33112555, 2020). "Overall, these data further support a critical role for SOX9 in the mechanisms underlying fibrosis and indicate the value of investigating SOX9-regulated pathways as serum biomarkers or as potential targets to reduce fibrosis and its progression to cirrhosis and HCC." (PMID 30559459, 2018). "A clinical biopsy study of cirrhosis has found that the SOX9 expression levels in chronic liver disease is related to the severity of fibrosis, and thus can precisely predict cirrhosis progression." (PMID 36725885, 2023). "In stage 4 fibrosis (cirrhosis stage), this SOX9 + HepPar1 + pseudo-rosette formation occurred inside the portal region and was lined with the ductular structure surrounded by collagen deposition." (PMID 35313986, 2022). "Nevertheless, p21 co-staining SOX9-positive LPLCs emerged unexpectedly in the cirrhosis stage in their own cell cluster." (PMID 35313986, 2022). "Through histological observation from the fibrosis to cirrhosis stage, we also found that bi-phenotypical SOX9 co-staining HepPar1 cells emerged from the parenchyma to the portal region." (PMID 35313986, 2022). "Human cirrhotic and cirrhosis-associated HCC tissues showed an increase of IMP2 expression and of the progenitor cell markers SOX9, SPP1/osteopontin, CDH1/E-cadherin, AFP, PROM1/CD133, BEX1, EPCAM." (PMID 31555647, 2019). "Similar to mouse, liver biopsy samples from patients with advanced fibrosis secondary to chronic hepatitis C (CHC) showed high levels of all identified SOX9 targets in advanced fibrosis/cirrhosis (IS6)." (PMID 30559459, 2018). "Here, we show that prevalence of SOX9 in biopsies from patients with chronic liver disease correlates with fibrosis severity and accurately predicts disease progression toward cirrhosis." (PMID 29109128, 2017). "In this study, we show the prevalence of SOX9 in biopsies from patients with chronic liver disease correlated with fibrosis severity and accurately predicted disease progression toward cirrhosis." (PMID 29109128, 2017). "SOX9 expression in biopsies from patients with chronic hepatitis C was found to correlate with fibrosis severity and accurately predicted disease progression toward cirrhosis." (PMID 37296834, 2023). "Our further investigation into the association between these DEGs and immune infiltration also revealed the correlations between ACTB, TAGLN, VIM, SOX9 and immune cells, supporting that these genes play a vital role in cirrhosis via regulating immune infiltration." (PMID 36725885, 2023). "Importantly, elevated levels of SOX9 or SOX9-regulated matrix proteins have been shown to correlate with the progression toward cirrhosis in these patients." (PMID 34520400, 2021). "The positivity for SOX9 expression was independent of the presence of cirrhosis, one of the major risk factors for HCC." (PMID 29121666, 2017). "Besides, poor prognosis of HCC patients has been linked with high SOX9 expression independent of the presence of cirrhosis." (PMID 31057614, 2019). "Moreover, poor prognosis of HCC patients has been linked with high SOX9 expression independent of the presence of cirrhosis." (PMID 31057614, 2019).
Cirrhosis (continued). "Next, we analysed the correlation of SOX9 and CK19 expression with clinical parameters of the iCCA patients, including age, gender, vascular invasion, existence of cirrhosis and American Joint Committee on Cancer (AJCC) classification." (PMID 30420613, 2018). "During fibrosis stages 0–3, SOX9-negative hepatocytes showed increasing Ki67 positivity from 0.61 to 3.73%, while their Ki67 positive staining decreased to 0.94% in the cirrhosis stage." (PMID 35313986, 2022). "As expected, the Ki67 positivity of LPLCs increased gradually from the fibrosis stage to the cirrhosis stage, while the Ki67 co-staining was decreased in SOX9-negative hepatocytes in the cirrhosis stage." (PMID 35313986, 2022). "In the cirrhosis stage (fibrosis stage 4), the p21 positivity of SOX9-negative hepatocytes was almost at the same level as that of LPLCs, i.e., 0.94% and 0.74%, respectively." (PMID 35313986, 2022). "Altogether, these results suggest that the SOX9 activation network and the expansion of liver progenitor cells either by increased survival or the dedifferentiation of hepatocytes are common mechanisms of fibrosis progression in NASH and other chronic liver diseases leading to cirrhosis." (PMID 37296834, 2023). "However, the Ki67 positivity of the LPLC cluster gradually increased and reached 1.15% in the cirrhosis stage, which was higher than that of the SOX9-negative hepatocyte cluster (1.09%)." (PMID 35313986, 2022).
triple-negative breast carcinoma (15 papers, 2019 to 2026). An invasive breast carcinoma which is negative for expression of estrogen receptor (ER), progesterone receptor (PR), and human epidermal growth factor receptor 2 (HER2). "For triple-negative breast cancer, multi-epitope vaccines targeting SOX9 have been designed to induce potent cellular and humoral immunity." (PMID 41293317, 2025). "SOX9 has recently been considered a key regulator of triple-negative breast cancer (TNBC) metastasis." (PMID 41293317, 2025). "Since SOX9 promotes proliferation, migration, and invasion in human basal-like triple-negative breast cancer cell, we decided to explore the consequences of HuR silencing on such parameters in Hs578T and BT549 cell lines." (PMID 38254873, 2024). "Through a bioinformatics analysis of the gene expression profile of the Hs578T basal-like triple-negative breast cancer cell line with silenced HuR, we have identified SOX9 as a potential HuR-regulated target." (PMID 38254873, 2024). "One publication reports that TNFRSF10C plays a role in triple-negative breast cancer cell survival and metastasis regulated by SOX9." (PMID 34256750, 2021). "Future experiments aimed at evaluating whether overexpression of MALAT1 in cell models of basal-like triple-negative breast cancer reverses the stabilization of SOX9 mRNA could help assess the role of MALAT1-HuR in EMT regulation." (PMID 38254873, 2024). "Finally, we demonstrated that silencing HuR negatively affects the migration and invasion abilities of Hs578T and BT549 human basal-like triple-negative breast cancer cells in a way that mimics the phenotype of SOX9-silenced cells." (PMID 38254873, 2024). "Therefore, we selected the triple-negative breast cancer cell line MDA-MB-231 with sustained SOX9 expression." (PMID 35779228, 2023). "Furthermore, Sox9 silencing reduced the capacity of tamoxifen-resistant cells and triple-negative breast cancer cells to form colonies, inhibited anchorage-independent growth in soft agar and significantly reduced capacity for invasion." (PMID 30622340, 2019). "Furthermore, both primary and secondary mammosphere formation efficiency was diminished in MCF7TamR cells by reducing Sox9 expression levels using two different shSox9 sequences and also in triple-negative breast cancer cells." (PMID 30622340, 2019). "SOX9 is a transcription factor involved in promoting EMT, metastasis, survival, and the maintenance of cancer stem cells (CSCs) in triple-negative breast cancer." (PMID 38254873, 2024). "Additionally, CDH6 correlated with stem-cell-related transcription factors, including FOXM1, SNAI1, SOX9, and MCM2, in triple-negative breast cancer." (PMID 35938030, 2022). "Additionally, we observed that THZ2 reduces SOX9 protein levels in GBM cells, suggesting that CDK7 inhibition may enhance TMZ sensitivity by suppressing SOX9 expression, similar to its role in triple-negative breast cancer." (PMID 40843352, 2025). "Therefore, the combinatorial treatment of triple-negative breast cancers with FGFR and AKT inhibitors may target two distinct signaling pathways that drive SOX10 expression by blocking both the induction and activation of Sox9." (PMID 33985544, 2021). "Intriguingly, Sox9 inhibition (whether transient or stable) resulted in significantly reduced expression of AXIN2, a classical Wnt/β-catenin target gene and of the Wnt receptor and target gene FZD4, in tamoxifen-resistant cells and in triple-negative breast cancer cells." (PMID 30622340, 2019).
endometrial cancer (14 papers, 2015 to 2025). Primary or metastatic malignant neoplasm involving the endometrium (mucous membrane that lines the endometrial cavity). "This is also true for endometrial cancer, as SOX9 has been reported as an independent risk factor for endometrial hyperplasia in the uterine epithelium, which is a precursor to endometrial cancer." (PMID 37511248, 2023). "The Human Protein Atlas and our preliminary data demonstrated that high expression of APH1A, GDH2, SETDB1, and SOX9 are associated with low survival in endometrial cancer." (PMID 36230806, 2022). "We also linked the SOX9+LGR5+ signals to the four molecular subtypes of endometrial cancer defined by TCGA30." (PMID 34857954, 2021). "In addition, overexpression of SOX9 was found to cause proliferation of endometrial cancer cells." (PMID 37511248, 2023). "By defining the transcriptomes of our two SOX9 populations, we can show the specific cell signals that dominate in endometrial carcinomas and endometriosis." (PMID 34857954, 2021). "SOX9 is also upregulated in endometrial cancer and upregulation of SOX9 is a feature of the premalignant hyper-proliferative condition, endometrial hyperplasia, suggesting an involvement of the basalis progenitor ASC in these conditions." (PMID 30347708, 2018). "In endometrial cancer, upregulation of SOX9 could promote endometrial cell proliferation, induce endometrial precancerous lesions, and predict the prognosis of endometrial cancer patients in combination with the expression of other genes." (PMID 36003340, 2022). "SOX9 overexpression in uterine epithelium may induce endometrial hyperplastic lesions, promoting endometrial cancer cell proliferation." (PMID 33579221, 2021). "The panel included previously reported endometrial cancer stem cell markers (CD44, ALDH1 and CD133), normal endometrial stem cell markers (SOX9 and CD15) and universal stem cell marker." (PMID 39888143, 2025). "Linc-ROR/miRNA axis-mediated SOX9 activation might not be the only mechanism for regulating cancer stemness in ESCC, given that miR-145 has also been reported to enhance aggressive phenotypes by targeting NANOG in pancreatic and endometrial cancer." (PMID 29237490, 2017).
esophageal cancer (14 papers, 2015 to 2024). A primary or metastatic malignant neoplasm involving the esophagus. "SOX9 has been implicated in the induction of a cancer stem cell phenotype in esophageal cancer." (PMID 26447543, 2015). "Further research discovered that Hippo coactivator YAP1 stimulates SOX9 expression in esophageal cancer cells, resulting in these cancer cells exhibiting stem cell-like characteristics." (PMID 37183261, 2023). "It was shown that the YAP1/TEAD complex transcriptionally regulates the SOX9 gene in esophageal cancer." (PMID 36180487, 2022). "YAP was found to regulate the EMT-associated genes by inducing SOX-2 expression in cooperation with Oct-4 in NSCLC cells 12 and to directly up-regulate SOX-9 and induce stem-like properties in esophageal cancer cells." (PMID 33442415, 2021). "In lung and esophageal cancers Sox9 is activated by Notch pathway and in the esophagus, Sox9 is also a YAP1 target." (PMID 27105493, 2016). "In esophageal cancer, the Hippo coactivator Yes-associated protein 1 (YAP1) upregulates SOX9 transcription by binding to the SOX9 promoter, upregulating SOX9 expression, followed by the acquisition of cancer stem cell properties." (PMID 26384302, 2015). "Our current data and previous report in esophageal adenocarcinoma suggest that activation of SOX9 by YAP via TEAD-mediated transcription might be the uniform driver for endowing CSC-like properties in both histological subtypes of esophageal carcinoma." (PMID 30401982, 2019). "SOX9 is known to drive columnar differentiation of the esophageal squamous epithelium and has been described to attribute stem cell-like properties to esophageal cancer cells." (PMID 26447543, 2015). "In esophageal cancer, YAP1 was shown to confer cancer stem cell properties by activating SOX9 via TEAD-mediated binding." (PMID 36045416, 2022). "Our previous study demonstrated that YAP1 confers CSCs properties to nontumorigenic cells and cancer cells by regulating SOX9 in esophageal cancer." (PMID 31601234, 2019). "Yap1 directly upregulated SOX9, and served as a primary determinant of TIC properties in non-transformed cells and in esophageal cancer cells." (PMID 26695440, 2016). "Upstream of SOX9, YAP1 has been shown to be a major determinant of cancer stem cell properties in non-transformed and esophageal cancer cells." (PMID 26447543, 2015).